CERKL (CERK like autophagy regulator)
Description:
Has no detectable ceramide-kinase activity. Overexpression of CERKL protects cells from apoptosis in oxidative stress conditions.
Synonyms: RP26
Tractability: PROTAC: ubiquitination databases record sites on it.
Safety:
Unwanted effects reported when the protein is acted on. In parentheses: how it was acted on, where the effect was seen, and who reports it.
adverse cardiovascular events (source: ClinPGx)
Gene: Protein-coding gene on chromosome 2 (181,535,041 to 181,680,665, reverse strand). Ensembl gene ENSG00000188452.
Subcellular location: Cytoplasm; Nucleus, nucleolus; Cytoplasm (Isoform 2); Golgi apparatus, trans-Golgi network; Endoplasmic reticulum
Subcellular location (Human Protein Atlas): Cytosol; Nucleoplasm
Gene Ontology:
Molecular function: protein binding; kinase activity; sphingolipid binding
Cellular component: plasma membrane; cytoplasm; endoplasmic reticulum; Golgi apparatus; nucleolus; nucleus; perinuclear region of cytoplasm; photoreceptor inner segment; photoreceptor outer segment
Genetic constraint (gnomAD): Loss-of-function variants: 45 observed, 40.35 expected, observed/expected ratio (o/e) 1.12, 90% interval 0.88 to 1.43. The upper end of that interval is the gene's LOEUF score, 1.43, which puts it in group 5 of 6, group 1 being the genes least tolerant of losing a copy. Missense variants: 473 observed, 464.3 expected, observed/expected ratio (o/e) 1.02, 90% interval 0.94 to 1.1. Synonymous variants: 185 observed, 167.68 expected, observed/expected ratio (o/e) 1.1, 90% interval 0.98 to 1.25.
Gene-disease validity (ClinGen):
ClinGen rates the evidence that CERKL causes each of these diseases.
CERKL-related retinopathy (autosomal recessive): Definitive. An inherited retinopathy caused by bi-allelic variants in the CERKL gene.
Homologues: Orthologues: chimpanzee CERKL (100% identical), macaque CERKL (98% identical), rabbit CERKL (87% identical), pig CERKL (86% identical), dog CERKL (84% identical), rat Cerkl (76% identical), mouse Cerkl (73% identical), tropical clawed frog cerkl (58% identical), zebrafish cerkl (56% identical), Drosophila melanogaster Cerk (25% identical), Caenorhabditis elegans cerk-1 (22% identical), Drosophila melanogaster Sk1 (18% identical), and 2 more. Paralogues in human: CERK (28% identical), SPHK2 (19% identical), AGK (16% identical), SPHK1 (16% identical).